RNU6-986P (RNA, U6 small nuclear 986, pseudogene)
Gene: Small nuclear RNA gene on chromosome 2 (27,475,494 to 27,475,595, reverse strand). Ensembl gene ENSG00000200003.
Homologues: Orthologues: chimpanzee U6 (100% identical), macaque U6 (99% identical). Paralogues in human: RNU6-1209P (89% identical), RNU6-797P (88% identical), RNU6-1287P (87% identical), RNU6-16P (87% identical), RNU6-742P (87% identical), RNU6-1083P (86% identical), RNU6-1181P (86% identical), RNU6-11P (86% identical), RNU6-1243P (86% identical), RNU6-1309P (86% identical), RNU6-37P (86% identical), RNU6-480P (86% identical), and 1286 more.